CDK1 (cyclin dependent kinase 1)
Diseases named in the same sentence as CDK1 in open-access papers (continued):
Sharing a sentence is not in itself a finding about the gene and the disease.
cancer (continued). "Furthermore, CDK1 has been considered as an underlying diagnostic and cancer progression biomarker as well as a drug target for ESCA." (PMID 34987580, 2021). "As CDK1 and c-Myc are implicated in tumorigenic events and cap-dependent mRNA translation is deregulated in many cancers, this raises the potential of utilizing the mRNA capping enzymes as therapeutic targets to selectively inhibit protein synthesis in cancer cells." (PMID 30991934, 2019). "The molecular mechanisms underlying the role of CDK1 in human cancers await more research." (PMID 31886163, 2019). "Overexpression of CDK1 has been associated with several cancers, in particular in EOC increased expression of CDK1 correlated with poor prognosis, and may also be a valuable biomarker for EOC to incorporate into a potential prognostic algorithm." (PMID 30279418, 2018). "Indeed, negligible cancer-associated mutations are reported for Aurora kinase B, Cdk1, Cyclin B, Nek2, and Pin1, proteins involved in initial events of mitosis." (PMID 25999914, 2015). "Moreover, a recently published study has shown that UHRF1 depletion in cancer cells causes G2/M cell cycle arrest and apoptosis accompanied with phosphorylation of cyclin-dependent kinase 1 (CDK1) which is in agreement with our present data." (PMID 23688286, 2013). "Accumulating evidence demonstrated that both the CyclinB1 and CDK1 overexpression could contribute to cancer risk and progressions." (PMID 24386390, 2013). "Thus, CDK1 and its activating machinery components were broadly identified as factors that underlie sensitivity to many agents used to treat human cancers, especially microtubule-directed agents." (PMID 21887332, 2011). "Finally, CDK1 could be implicated in the progression of specific cancer as observed in prostate carcinomas where it phosphorylates Androgen Receptor (AR), which results in decreased transactivation upon androgen stimuli." (PMID 39800748, 2025). "Therefore, we hypothesized that the reversal of TAMs’ pro-cancer effects by chrysin may be linked to the suppression of CDK1 expression." (PMID 38675475, 2024). "Thus, these bioinformatic analyses support the hypothesis that loss of CDKN1A expression associated with unleashed CDK1 can be linked to CIN in human cancer." (PMID 33168930, 2021). "Notably, p‐TFCP2L1 and CDK1 were highly expressed in tumor tissues of BC patients with aggressive clinicopathological features, and this expression was associated with significantly shorter cancer‐specific survival." (PMID 31709755, 2020). "High levels of co‐expression of p‐TFCP2L1 and CDK1 were associated with aggressive clinicopathological features, such as high tumor grade (P < 0.001) and frequent muscularis propria invasion (P = 0.041), distant metastasis (P = 0.040), and cancer‐specific death (P < 0.001)." (PMID 31709755, 2020). "In patients with BC, high co‐expression of TFCP2L1 and CDK1 was associated with unfavorable clinical characteristics including tumor grade, lymphovascular and muscularis propria invasion, and distant metastasis and was an independent prognostic factor for cancer‐specific survival." (PMID 31709755, 2020). "However, rather high expression of CDK1 expression can cause paclitaxel resistance in cancer cells." (PMID 29416675, 2018).
cancer (continued). "Although this study supports the role of EGR3 as an oncogenic driver in GBM by promoting cell growth and upregulating MYC and CDK1, its function in cancer appears to be complex and context-dependent." (PMID 40649712, 2025). "Overexpression of CDK1 has been detected in multiple cancer types, identifying it as a universal pan-cancer biomarker." (PMID 40282517, 2025). "Phosphorylated cyclin-dependent kinase 1 (CDK1), which is involved in unrestricted cell proliferation is proposed as a promising target for cancer treatment." (PMID 40551232, 2025). "Dual inhibition of CDK2 and CDK1 activity was explored to prevent polyploid cancer cells from reentering the cell cycle, forcing them into eliciting an apoptotic death program." (PMID 40232858, 2025). "In the context of cancer CDK1, by phosphorylating multiple factors, plays a major role in promoting cell transformation and tumorigenesis." (PMID 39800748, 2025). "We discovered that CDK1 was substantially expressed in cancer tissue as compared to the control group." (PMID 39991589, 2025). "The as-prepared NBS provided both easy detection of CDK1, reported the enzymatic activity of CDK1, and detected the CDK/cyclin activity in numerous cancer types, usually associated with poor prognosis." (PMID 40710305, 2025). "In particular, ERBB2 has been shown tophosphorylate cyclin-dependent kinase CDK1, increasing theresistance of cancer cells to apoptosis induced by the cytostaticanticancer drug paclitaxel." (PMID 41541554, 2025). "Given that CDK1–cyclin complexes control the 3D migration of normal and cancer cells, we next tested their role in long-range invasion through 3D collagen-I gels." (PMID 40518827, 2025). "This is in line with previous work linking increased levels of CDK1 to inferior survival rates and unfavorable clinical outcomes, solidifying CDK1 as an important prognostic marker for many cancers." (PMID 40282517, 2025). "The cell cycle regulatory network plays a crucial role in cancer development and progression, with cyclin-dependent kinase 1 (CDK1) emerging as a pivotal regulator of the G2/M phase transition." (PMID 41009727, 2025). "Apoptosis-resistant polyploid cancer cells persist and are enriched for the CDK1 pathway and KIF families." (PMID 40232858, 2025). "The occurrence of abnormal mitosis, which is triggered by the CCNB1/CDK1 complex, plays a significant role in the genesis and progression of cancer." (PMID 40198519, 2025). "In summary, our major findings identify differential roles for cyclin–CDK1 complexes in regulating cell motility and invasion in 3D matrices in normal and cancer cells." (PMID 40518827, 2025). "CDK1, a key regulator of the cell cycle, controls the transition from the G2 phase to mitosis —a process often dysregulated in cancer." (PMID 41162745, 2025). "We detected that green tea extract enables the inhibition of cell proliferation through suppression of cyclin B1 and CDK1 expression (or CDK1 activity) in PC3 cancer cells." (PMID 40336533, 2025). "Combined targeting of CDK2 with CDK1 or kinesin family member antagonists should eliminate polyploid cancer cells, promote apoptosis, and augment antineoplastic effects." (PMID 40232858, 2025). "It was reported that prolonged CDK2 inhibition increased cancer cell reliance on the CDK1 pathway, while rapid adaptation depended on expression of the CDK4/6 pathway." (PMID 40232858, 2025). "ATG10 promotes cancer growth and metastasis by modulating epithelial-mesenchymal transition and cell cycle regulators such as cyclin B1, CDK1 and CDK2." (PMID 40313244, 2025). "HSP90 is overexpressed in HB and aids cancer cell survival by stabilizing proteins like CDK1, a critical regulator of cell cycle progression." (PMID 40282517, 2025). "This investigation demonstrated that kaempferol affects cancer cells by downregulating CDK1, CDK4, CDK6, and CDK7 at both the gene and protein levels in MDA-MB-231 cells, and specifically CDK6 and CDK7 in MDA-MB-468 cells." (PMID 41463161, 2025).
cancer (continued). "Additional evidence for the antiproliferative potential of phenylpropanoids comes from studies on cinnamaldehyde and its analogs, which induced G2 arrest in human cancer cells by downregulating key G2/M regulators (CDK1, CDC25C, MAD2, CDC20)." (PMID 41009502, 2025). "The results indicated that compound 150441 effectively inhibited the expression of Aurora A and cyclin B1 and the activation of PLK1, CDK1, and CDC25C, causing cancer cell arrest in the G2 phase." (PMID 40126184, 2025). "In many types of cancer, CDK1 is frequently observed to be overexpressed or activated, leading to enhanced tumor proliferation, invasion, and metastasis." (PMID 41439111, 2025). "Inhibiting CDK1 expression and activation effectively suppresses cancer cell activity in various cancers." (PMID 40487391, 2025). "A deeper understanding of the differential role of CDK1 in cancer versus normal cells is critical for optimizing therapeutic windows and minimizing adverse effects." (PMID 40695806, 2025). "Recently, the importance of CDK1 inhibition in cancer therapy was the subject of a review, and overexpression of EGFR is common in LC." (PMID 39995112, 2025). "Using bioinformatics analysis, we evaluated the functional enrichment and role of the co-expressed gene CDK1 in these two cancers and its impact on their prognoses." (PMID 39991589, 2025). "We next sought to corroborate the role for cyclin–CDK1 complexes in mediating invasive migration in an alternative cancer type." (PMID 40518827, 2025). "Small-molecule inhibitors against CDK1 have shown antitumor activity in multiple cancer models, providing new hope for the treatment of HCC." (PMID 40332418, 2025). "CDK1 is a vital regulator of the cell cycle and plays an essential role in the development of cancer." (PMID 40000619, 2025). "We also found that cyclin B1 and CDK1 expression (or CDK1 activity) was inhibited by green tea extract in PC3 cancer cells." (PMID 40336533, 2025). "The proportions of cancer cells_CDK1 and cancer cells_MMP7 were similar between the “PFS < 6 m” and “progression” groups." (PMID 41016944, 2025). "Using RNA-Seq analyses of 4N as compared with 2N populations, it was found that persistent cancer cells were enriched for CDK1-dependent pathways." (PMID 40232858, 2025). "RO-3306, a selective small-molecule inhibitor of CCNB1/CDK1, has been widely used in cancer-related research." (PMID 40430484, 2025). "We treated cancer tissue and normal organ tissue with immunohistochemistry (IHC) to confirm the expression of CDK1 in CC tissue and normal cervical tissue, as well as CDK in OC tissue and normal ovarian tissue." (PMID 39991589, 2025). "Recently, several CDK1 inhibitors have been developed as therapeutic strategies for cancer treatment." (PMID 40299539, 2025). "This suggests that CDK1 plays a conserved role in regulating cell migration in both normal and cancer cells; however, the role for CDK1 in mediating cell migration in 2D and 3D environments remains poorly defined." (PMID 40518827, 2025). "As a therapeutic target, CDK1 has gained significant attention for its potential in cancer treatment, with inhibitors being particularly promising." (PMID 40746552, 2025). "Highlighted Article:Cyclin–CDK1 complexes have a previously undiscovered role in regulating normal and cancer cell migration in 3D matrices." (PMID 40518827, 2025). "For instance, CDK1 and BUB1 have been associated with aggressive behavior in cancers, but their direct involvement in environmental chemical–induced lung carcinogenesis had not been demonstrated." (PMID 41181148, 2025).
cancer (continued). "Each of these expressed genes are involved in CDK1 pathway regulation or in centrosome clustering of cancer cells having supernumerary centrosomes." (PMID 40232858, 2025). "Compared with the resistant cases, the sensitive cases presented a significantly lower proportion of cancer cells expressing CDK1 (P = 0.019) and a trend toward a greater proportion of cancer cells expressing MMP7 (P = 0.067)." (PMID 41016944, 2025). "CDK1+ cancer cells and TK1+ cancer cells, which have high levels of cell cycle activity, were abundant in resistant cases." (PMID 41016944, 2025). "In preclinical research, the use of CDK1 inhibitors has been explored as a possible therapeutic approach for cancer therapy." (PMID 38891892, 2024). "• Caused mouse cancer cells to enter a G2/M phase of cell cycle arrest in vivo.• Prevented the CDC25B substrate, CDK1 from being dephosphorylated." (PMID 38606093, 2024). "In summary, our analysis identified six different cancer cell subclusters, excluding premalignant Ep_FXYD2 and cycling Ep_CDK1 clusters." (PMID 38297291, 2024). "The Ep_CDK1 cluster represents proliferating cancer epithelial cells, which can be identified with prominent cell cycle signatures." (PMID 38297291, 2024). "The subsequent target of CDK1 via inhibitors such as cucurbitacin E (CurE), with and without mitotane exhibited good safety and efficacy for the treatment of cancer." (PMID 38169587, 2024). "After GluOC treatment, cyclin A2, cyclin B1 and CDK1 increased, while Y-27632 suppressed cell cycle progression in cancer cells." (PMID 39054484, 2024). "CDK1 plays a critical role in cancer progression and cancer cell survival and has emerged as one of the potential targets for tumour therapy." (PMID 38842135, 2024). "CDK1 is an important emerging target in cancer that plays a key role in cell cycle progression through G2/M phase transitions and activation of homologous recombination (HR) DNA repair pathways." (PMID 38967843, 2024). "Many inhibitors targeted to CDK1 have shown promising results in decreasing cancer cell progression and have entered clinical trials." (PMID 39433125, 2024). "We note that CDK1 regulates pyrodeath, apoptosis, and necrosis of cancer cells (PANoptosis) by binding to PANoptosomes in a ZBP1-dependent manner." (PMID 38967843, 2024). "Several small compounds have been created to specifically block CDK1, thereby halting the proliferation of cancer cells." (PMID 38895552, 2024). "Inhibition of CDK1 expression and activation effectively suppresses the function of many cancer cells." (PMID 38370368, 2024). "CDK1 inhibitors is an important target for cancer treatment and are already involved in some clinical trials." (PMID 38246945, 2024). "To date, CDK4/6 inhibitors and CDK1/2 inhibitors are widely used in clinical therapies or under clinical trials because of their pan-cancer killing effects." (PMID 38963708, 2024). "Consistent with the microtubule‐targeting activity of VU‐0365114, cancer cells with higher levels of mitotic regulators (CDK1, CCNB1, and STMN1) were more sensitive to VU‐0365114." (PMID 37842807, 2024). "The filtered blue module (203 genes) contained several genes associated with various typesof cancers and cell cycle regulation, including TTK, PLK1, LRG1, and CDK1." (PMID 39439565, 2024). "It has been reported that CDK1 promotes cancer cell migration and metastasis by phosphorylating proteins such as EZH2 and activating pathways such as Wnt/β‐Catenin and the ERK/GSK3β/SNAI axis." (PMID 38842135, 2024). "CKS2 can increase cyclin, cyclin A, cyclin B1 and CDK1, thereby promoting cancer cell proliferation." (PMID 39188686, 2024).
cancer (continued). "Four key genes CCL2, CCR7, LY96, and PTPRC, from ClusterK1 and five genes AURKA, CDK1, CCNA2, FEN1, and PLK1 from ClusterK2, were associated with at least one type of cancer." (PMID 38872418, 2024). "Ro-3306, a specific inhibitor of CDK1, has been demonstrated to suppress tumor growth across various types of cancer." (PMID 38638876, 2024). "HMMR’s association with key cell cycle regulators (AURKA, TPX2, and CDK1) underscores its pivotal role in cancer initiation and advancement." (PMID 38576486, 2024). "Given that altered chromatin dynamics lead to an accelerated cell cycle, which in turn increases cancer risk, it becomes crucial to further investigate how SRSF9 affects CDK1 and other genes." (PMID 38842611, 2024). "Overall, dysregulation of CDK1 is an important target for cancer treatment and is essential for its growth." (PMID 38891892, 2024). "Inhibition of CDK1 activity can lead to cell cycle arrest and decrease the growth and proliferation of cancer cells." (PMID 38069284, 2023). "Despite its unclear activation state in cancer, CDK1 has emerged as an attractive target for therapeutic intervention." (PMID 37898722, 2023). "This review evaluates the mechanisms and implications of targeting CDK1 in tumorigenesis and cancer therapy." (PMID 37311884, 2023). "The results indicate that CDK1 integrating proteins are involved in signaling pathways in cancer, cell cycle, and microRNAs." (PMID 37311884, 2023). "In other cancers, inhibition of cell cycle progression was shown to be caused by the reduction of CCNB1 and CDK1 expression induced by the inhibition of HSP90." (PMID 37547755, 2023). "Using the STRING database, we then obtained the interacting network of CDK1 and its interacting proteins in pathways in cancer." (PMID 37311884, 2023). "Since CDC25C is commonly overexpressed in cancer cells to facilitate G2/M transition by dephosphorylating CDK1, we assessed the phosphorylation level of CDK1 at Y15 (p-CDK1-Y15)." (PMID 38062028, 2023). "Activation of cell cycle regulators, including CDK1, induces cell death through apoptosis by enhancing cell cycle progression in cancer cells harboring DNA abnormalities, including DSBs generated by the inhibition of SSB and DSB repair processes." (PMID 36765693, 2023). "Further preclinical studies including PDX in vivo animal models and clinical studies are warranted to explore the therapeutic benefits of targeting the PIN1/CDK1-pVHL axis in the treatment of multiple human cancers with wild-type VHL." (PMID 36813923, 2023). "Despite their potential, to date, limited preclinical studies have been performed to assess their efficacy in targeting alterations of CDK1 in cancer." (PMID 37898722, 2023). "We aim to elucidate the molecular mechanism by which PIN1 and CDK1 cooperatively modulate pVHL stability, contribute to tumor progression and explore their therapeutic potential in the treatment of cancers with wild-type VHL including TNBC." (PMID 36813923, 2023). "Overall, our study provides important preclinical evidence that targeting PIN1/CDK1 axis is an appealing strategy to suppress tumor growth and metastasis, and sensitize cancer cells to chemotherapies by stabilizing pVHL in TNBC." (PMID 36813923, 2023). "We used TIMER2.0 and CGGA for a comprehensive and systematic CDK1/PBK/CHEK1 oncogenic signature analysis for their differential expression in pan cancers and their correlation in GBM." (PMID 38003585, 2023). "Inhibition of the expression and activation of CDK1 effectively suppresses oncogenic cell function in many cancer types." (PMID 37311884, 2023). "CDK1 activation plays a critical role in a wide range of cancer types; and CDK1 phosphorylation of its many substrates greatly influences their function in tumorigenesis." (PMID 37311884, 2023).